ENSG00000255054 (novel protein)
Gene: Protein-coding gene on chromosome 1 (25,811,470 to 25,823,744, forward strand). Ensembl gene ENSG00000255054.
Genetic constraint (gnomAD): Missense variants: 42 observed, 54.57 expected, observed/expected ratio (o/e) 0.77, 90% interval 0.6 to 1. Synonymous variants: 18 observed, 24.25 expected, observed/expected ratio (o/e) 0.74, 90% interval 0.51 to 1.1.